TRPM4 (transient receptor potential cation channel subfamily M member 4)
Diseases named in the same sentence as TRPM4 in open-access papers (continued):
Sharing a sentence is not in itself a finding about the gene and the disease.
prostate carcinoma (continued). "We demonstrated that TRPM4 protein levels in areas of PIN and human prostate cancer tissues rated with different Gleason scores were elevated compared to TRPM4 expression in healthy tissue or areas of BPH." (PMID 26496025, 2015). "We here investigated the role of TRPM4 in prostate cancer cells that - in contrast to hPEC - are characterized by several pathophysiological changes in cellular functions such as unlimited proliferation and enhanced migration potential." (PMID 26496025, 2015). "Interestingly, in addition to genes linked to colorectal or prostate cancer, there were also two genes known to be associated with both of those cancer types: CYB5D2 and TRPM4." (PMID 41234971, 2025). "At the mRNA level, MCOLN2 and TRPM4 were strongly expressed in a sub-set of prostate cancers." (PMID 40332161, 2025). "Moreover, in contrast to the results in endometrial cancer, in vitro studies showed a decreased expression of EMT factor Snail1 and mesenchymal N-cadherin in prostate cancer cells after the knock-down of TRPM4 and up-regulation of epithelial E-cadherin." (PMID 40332161, 2025). "Transient receptor potential melastatin‐4 (TRPM4) is overexpressed in prostate cancer (PCa)." (PMID 39821469, 2025). "In prostate cancer cells, several TRPM4‐specific alterations of Ca2+ signaling have been reported." (PMID 39821469, 2025). "Transient receptor potential melastatin‐4 (TRPM4) ion channel expression is upregulated in prostate cancer (PCa), contributing to increased cell proliferation, migration, adhesion, epithelial‐to‐mesenchymal transition, cell cycle shift, and alterations of intracellular Ca2+ signaling." (PMID 39821469, 2025). "In addition, the findings from some studies of prostate cancer cell lines suggest a more general role of TRPM4 in calcium-induced exocytosis in cancer cells." (PMID 35681487, 2022). "Accordingly, TRPM4 overexpression is correlated with higher grade prostate cancer." (PMID 36158191, 2022). "TRPM4 channel is among the five candidate driver genes implicated in non-hormonal prostate cancer (PCa)." (PMID 36844925, 2022). "Next, we hypothesized whether the Ca2+-induced, TRPM4-dependent increase in cell capacitance is characteristic of CRC cells or whether there is a similar effect in prostate cancer (PCa) cell lines that also express high levels of TRPM4." (PMID 35681487, 2022). "TRPM4 has been shown to play an oncogenic role in prostate cancer." (PMID 34360952, 2021). "Similarly, in a study of 614 patients, significantly higher TRPM4 staining intensity was found in glands of prostate cancer compared with benign glands." (PMID 35056097, 2021). "TRPM4 can be a driver gene of androgen-independent prostate cancer in vitro." (PMID 35056097, 2021). "TRPM4 overexpression in lymph node carcinoma of the prostate cell line increased the total levels of β-catenin, proposing a role for TRPM4 channels in β-catenin oncogene signaling and again enforcing TRPM4 as a new potential target for future therapies in prostate cancer." (PMID 35056097, 2021). "Moreover, PC3 prostate cancer cells express 10-fold more TRPM4 mRNA than normal prostate epithelial cells." (PMID 34360952, 2021). "Interestingly, TRPM4 is highly expressed in androgen-sensitive prostate cancers required for their aggressive phenotypes." (PMID 32484822, 2020). "Independent investigations have shown the oncogenic roles of TRPM4 in prostate cancer." (PMID 32484822, 2020). "Transient receptor potential melastatin‐4 channel (TRPM4) is expressed in several human tissues and has been identified as a cancer driver gene that contributes to migration, proliferation, and invasion of prostate cancer (PCa) cells." (PMID 31441200, 2019). "In addition, TRPM4 was reported to be overexpressed in prostate cancer, where its increased expression promoted the stabilization and activity of β-catenin enhancing cell proliferation, but the underlying mechanisms have not yet been clarified." (PMID 29996905, 2018).
prostate carcinoma (continued). "TRPM4, a calcium‐activated monovalent‐selective cation channel, has been found to be overexpressed in a variety of human tumors, including prostate cancer." (PMID 28614631, 2018). "Actually, patients with prostate cancer display an elevation of gene expression of TRPM4." (PMID 29875336, 2018). "In RPE cells, we suppose that cAMP leads to the activation of protein kinase A, which in turn opens L-type Ca2+ (e.g., CACNA1A: 3.85 mFPKM; CACNA1A: 2.63 mFPKM) or TRP channels (e.g., TRPM3: 1.71 mFPKM; TRPM4: 7.76 mFPKM), as shown in epidermal melanocytes and prostate cancer cells." (PMID 29249973, 2017). "In addition, TRPM4 is a cancer-driver gene in androgen-insensitive prostate cancer [103•], and TRPM4 protein expression is upregulated in human prostate cancer tissue [104•, 105•]." (PMID 29951353, 2017). "Recently, TRPM4 was identified as a cancer driver gene in androgen-insensitive prostate cancer." (PMID 26496025, 2015). "TRPM4 conducted large Na+ currents in both, hPEC and in prostate cancer cell lines." (PMID 26496025, 2015). "One explanation may be that the transfection of prostate cancer cells itself has a clear impact on their proliferation which may cover any specific contribution of TRPM4." (PMID 26496025, 2015). "Even though the current in DU145 and PC3 cells may be lower than in native cancer cells, here, DU145 and PC3 serve as model cell lines to investigate the function of TRPM4 in androgen-insensitive prostate cancer." (PMID 26496025, 2015). "As in human prostate cancer tissue TRPM4 was up-regulated; in native cancer cells, TRPM4 currents might well exceed TRPM4 currents in hPEC, even though under the conditions used here TRPM4 currents in cancer cell lines were lower than in hPEC." (PMID 26496025, 2015). "Moreover, increases in TRPM4 mRNA have been observed in prostate cancer, in B-cell non-Hodgkin lymphoma and in a human cervical-uterine tumor samples and cervical-uterine cancer derived cell lines." (PMID 26110647, 2015). "In patients with prostate cancer, gene expression of TRPM4 is elevated." (PMID 26496025, 2015). "Thus, we investigate the function of TRPM4 in androgen-insensitive prostate cancer cells DU145 and PC3." (PMID 26496025, 2015). "However, elevated levels of TRPM4 expression have been observed in breast and prostate cancer, indicating that its role might be cancer type specific." (PMID 34936030, 2021). "Moreover, in a recent study of a tissue microarray from 210 prostate cancer patients, a correlation between TRPM4 protein expression intensities (scores of 3 vs. 4, the second highest and highest TRPM4 scores, respectively) and both local and metastatic progression was described." (PMID 33562811, 2021). "Indeed, it was reported that in prostate cancer, TRPM4 is regulated by microRNA-150." (PMID 33291725, 2020). "Thus far, the role of TRPM4 in prostate cancer has been unclear." (PMID 26496025, 2015). "Thus the regulatory mechanism of TRPM4 on migration of prostate cancer cells may differ in DU145 and PC3 cells and include Ca2+ independent mechanisms." (PMID 26496025, 2015). "TRPM4 contributes to the migration and invasion of the PC3 prostate cancer cell line and alters epithelial-mesenchymal transition (EMT), a crucial process for cancer cell migration and invasion." (PMID 41343534, 2025). "In prostate epithelial (PEC) and prostate cancer (DU145) cells, TRPM4 knockdown significantly increased store-operated Ca2+ entry (SOCE)." (PMID 36844925, 2022). "In another prostate cancer cell line, human-derived DU145 cells, CBA was even less effective, as it reduced endogenous TRPM4 current by 55 and 65% at 3 and 50 μM, respectively." (PMID 35056138, 2022). "Interestingly, despite causing partial inhibition of TRPM4 currents in DU145 cells, the novel inhibitors CBA, NBA, and LBA did not evoke any TRPM4-specific effect in the cellular assays, which questions the role of TRPM4 ion conductivity in cancer hallmark functions in prostate cancer." (PMID 35056097, 2021).
prostate carcinoma (continued). "Upon activation, a Na+ influx via TRPM4 depolarizes the membrane potential, which reduces the driving force for Ca2+ and limits SOCE, and thus promotes migration of androgen-insensitive prostate cancer cells." (PMID 34630112, 2021). "Both healthy prostate (hPEC) and androgen-insensitive prostate cancer cell lines DU145 and PC3 possessed large TRPM4-mediated Na+ currents." (PMID 35056097, 2021). "The similarities in the expression profile of TRPM4 and AR in DCIS, breast and prostate cancers suggest a connection of TRPM4 with AR signaling pathway in tumors, and this warrants future investigations." (PMID 32484822, 2020). "We previously demonstrated that siRNA-based knockdown of TRPM4 increases SOCE and reduces cell migration in the prostate cancer cell lines DU145 and PC3 [105•, 106]." (PMID 29951353, 2017). "In primary human prostate epithelial cells (hPEC) from healthy tissue and in the androgen-insensitive prostate cancer cell lines DU145 and PC3, TRPM4 mediated large Na+ currents." (PMID 26496025, 2015). "We also functionally characterized TRPM4 in primary human prostate epithelial cells (hPEC) and in androgen-sensitive (LNCaP) and androgen-insensitive (DU145 and PC3) prostate cancer cell lines." (PMID 26496025, 2015). "Another study found increased levels of TRPM4 mRNA when human prostatic intraepithelial neoplasia (PIN; abnormal but somewhat premalignant cells) develop into prostate cancer cells." (PMID 26496025, 2015). "We found elevated TRPM4 protein levels in prostatic intraepithelial neoplasia (PIN) and prostate cancer tissue compared to healthy tissue." (PMID 26496025, 2015). "TRPM4 is responsible for Ca2+-activated non-selective (CAN) currents in prostate cancer, and TRPM4 knockdown reduces large Na+ currents following Ca2+ activation." (PMID 41343534, 2025). "The prognosis of prostate cancers with high TRPM4 expression was not different from the prognosis with counterparts having low TRPM4 mRNA expression." (PMID 40332161, 2025). "The TRPM4 protein was strongly expressed in histological samples of 20 prostate cancer patients, but weak or no expression was seen in benign prostatic hyperplasia tissues." (PMID 35056097, 2021). "TRPM4 mRNA and protein levels were overexpressed in prostate cancer tissues compared with non-malignant pancreatic ducts, and its overexpression conferred increased risk of biochemical recurrence in patients with prostate cancer." (PMID 32484822, 2020). "The key roles of TRPM4 in activating the β-catenin signaling pathway for the EMT and invasion of prostate cancer cells might also occur in breast cancer to activate EMT for metastasis that requires further investigations." (PMID 32484822, 2020). "For instance, in androgen-insensitive prostate cancer cells, it has been shown that TRPM4 acts as an important negative feedback regulator of SOCE, thus promoting cell migration." (PMID 33132914, 2020). "Using this approach, the RIS were identified near a known prostate cancer gene PTRF as well as other genes that were not previously implicated in prostate cancer including ATPAF1, GCOM1, MEX3D, and TRPM4." (PMID 27792127, 2016). "We suggest that up-regulation of the TRPM4 cancer driver gene functionally contributes to the development of PIN and prostate cancer by elevating the migration potential of androgen-insensitive prostate cancer cells." (PMID 26496025, 2015). "Finally, we determined the potential of TRPM4 to limit SOCE and the functional role of TRPM4 in cell migration and proliferation of prostate cancer cells." (PMID 26496025, 2015). "We did not observe any correlation between TRPM4 staining and the clinical or pathological stages of prostate cancer." (PMID 26496025, 2015). "The promoter of TRPM4 that is functional in prostate tissues and prostate cancer did not possess clustered binding sites for ERG, AR, TCF4 or Slug but did have multiple binding sites for SMAD transcription factors, suggesting dominant regulation by the TGFβ pathway." (PMID 40332161, 2025).
prostate carcinoma (continued). "Furthermore, it has been observed that the knockdown of TRPM4 was able to decrease the migration of androgen-insensitive prostate cancer cell lines DU145 and PC3 but not its proliferation." (PMID 33291725, 2020). "Another explanation could be that TRPM4 regulates proliferation in breast cancer cells while in prostate cancer TRPM4 does not impair proliferation." (PMID 26496025, 2015).
Stroke (27 papers, 2018 to 2026). Sudden impairment of blood flow to a part of the brain due to occlusion or rupture of an artery to the brain. "In stroke and other neurological diseases, Transient Receptor Potential Melastatin 4 (TRPM4) has been reported to cause oncotic cell death which is due to an excessive influx of sodium ions." (PMID 33195194, 2020). "Uncoupling NMDARs from TRPM4 or deleting TRPM4 has been shown to exert neuroprotective effects in both in vitro models and stroke mouse models, likely due to alterations in NMDAR signaling." (PMID 39687019, 2024). "Among the TRP superfamily, the transient receptor potential melastatin-like subfamily member 4 (TRPM4) has recently emerged as an important drug target for stroke therapy and many other diseases." (PMID 37239151, 2023). "We provide evidence showing that TRPM4 blocking antibody M4P can be an effective vascular protective agent in delayed stroke reperfusion." (PMID 37239151, 2023). "In conclusion, we identified the potential of TRPM4 blocking antibody M4P to ameliorate vascular injury during delayed stroke reperfusion." (PMID 37239151, 2023). "The application of siRNA to silence Trpm4 expression has been shown to decrease infarct volume in a rat model of permanent stroke, indicating that Trpm4 inhibition enhances the integrity of the blood–brain barrier following ischemic stroke reperfusion." (PMID 37569884, 2023). "The TRPM4-blocking antibody M4P has been shown to alleviate reperfusion injury and improve functional outcomes in animal models of early stroke reperfusion." (PMID 37239151, 2023). "In an animal stroke model, we found that TRPM4 expression is upregulated as early as 2 h after middle cerebral artery occlusion." (PMID 37239151, 2023). "In a rat model, TRPM4 was upregulated in cerebral endothelial cells 2 h after stroke reperfusion, and inhibition of TRPM4 by siRNA therapy reduced infarct volume and cerebral edema." (PMID 36061592, 2022). "M4P was shown to downregulate TRPM4 surface expression in rat models of stroke, and to inhibit hypoxia-induced cell swelling and reduce reperfusion injury in stroke recanalization." (PMID 33562811, 2021). "In the nervous system, TRPM4 contributes to the progression of multiple sclerosis, stroke, spinal cord injury, and head injury." (PMID 34771564, 2021). "M4P, which was originally designed to target rodent TRPM4, detected an upregulation of TRPM4 following stroke induction." (PMID 34002002, 2021). "In stroke, there are at least two types of cells that can be salvaged by TRPM4 blockade: neuron and vascular endothelial cell." (PMID 34002002, 2021). "Although TRPM4 has been well documented in stroke, the exact role of TRPM4 inhibition on oncotic cell death, particularly during the acute stage, remains largely unclear." (PMID 33195194, 2020). "M4P is capable of binding to TRPM4 in ischemic stroke and ameliorating reperfusion injury by improving blood-brain barrier integrity in a rat model of stroke reperfusion." (PMID 32484822, 2020). "Following stroke, hypoxia condition activates TRPM4 channel, and the sodium influx via TRPM4 is further enhanced by an increased TRPM4 expression." (PMID 33195194, 2020). "The most extensively studied TRPM channel in stroke is TRPM4 which has been found to play an important role in oncotic cell death." (PMID 33195194, 2020). "It should be noted that in these reports, TRPM4 level is very low in healthy tissues, and its upregulation occurs at least 2–6 h after stroke induction." (PMID 33195194, 2020). "Using M4P as a specific blocker for TRPM4, we are able to decipher how TRPM4 engages in disease progression immediately after ischemia which is common in stroke and many other disorders of central nervous system." (PMID 33195194, 2020). "It has been reported that the expression of TRPM4 is low in all cell types in the contralateral hemisphere after stroke." (PMID 33195194, 2020).